Y_RNA (Y RNA )
Gene: Miscellaneous RNA gene on chromosome 1 (164,854,231 to 164,854,332, forward strand). Ensembl gene ENSG00000201987.
Homologues: Orthologues: chimpanzee Y_RNA (100% identical), macaque Y_RNA (96% identical). Paralogues in human: RNY3 (89% identical), Y_RNA (87% identical), Y_RNA (86% identical), RNY3P1 (85% identical), Y_RNA (85% identical), Y_RNA (84% identical), Y_RNA (83% identical), RNY3P9 (82% identical), Y_RNA (82% identical), Y_RNA (81% identical), RNY3P11 (80% identical), RNY3P14 (80% identical), and 95 more.